ID1 (inhibitor of DNA binding 1)
Diseases named in the same sentence as ID1 in open-access papers (continued):
Sharing a sentence is not in itself a finding about the gene and the disease.
meningioma (1 paper, 2020). A generally slow growing tumor attached to the dura mater. "What is more, these genes, excluding ID1, ID3, and NMNAT2, were confirmed to be able to differentiate between the recurrence and nonrecurrence forms of meningioma (P < 0.05)." (PMID 32596316, 2020).
mesenchymal tumours (1 paper, 2017). "We saw considerable variability in ID1 expression in human colorectal lesions, with positive staining in the malignant epithelium of 24% (25/105) of tumours, consistent with the known frequency of mesenchymal tumours (cancer 1)." (PMID 28299802, 2017).
mesothelioma (1 paper, 2022). A usually malignant and aggressive neoplasm of the mesothelium which is often associated with exposure to asbestos. "The mechanism responsible for these effects is unknown, however we did observe both CBD and CBG treatment reduced expression of the pro-metastatic gene ID1 (inhibitor of DNA binding 1) in mesothelioma cells." (PMID 35954477, 2022).
metastasis (1 paper, 2022). The spread or migration of cancer cells from one part of the body (where they first appeared) to another. "In addition, ACVR2A, ID1, and ID4 are enriched in the TGF-β signaling pathway, and the role of TGF-β in osteolytic bone metastasis was well known." (PMID 35063044, 2022).
metastatic cancers (1 paper, 2015). A carcinoma which has spread from the original site of growth to another anatomic site. "Some tumor lymphangiogenic inhibitors such as deguelin, endostar, silencing Id-1, liposomal honokiol, mF4-31C1 and sVEGFR3-Ig have been reported as adjuvant antilymphangiogenic and antitumor drugs against some metastatic cancers in experiment and in clinic setting." (PMID 26187792, 2015).
metastatic melanoma (1 paper, 2015). A melanoma that has spread from its primary site to another anatomic site. "ID1 expression was found to be on average 2.5-fold higher (and up to 5.4-fold higher) in CD11B+ PBMCs from patients with metastatic melanoma (n=15) compared with healthy, age-matched controls (n=7, unpaired t-test, P<0.05)." (PMID 25924227, 2015). "Increased expression of the two downstream regulators of ID1, S100A8 and S100A9 levels was also observed (1.8- and 1.7-fold higher and up to 3.1- and 2.7-fold, respectively) in CD11B+ PBMCs from patients with metastatic melanoma compared with healthy, age-matched controls (unpaired t-test, P<0.01)." (PMID 25924227, 2015).
mismatch repair deficiency (1 paper, 2022). "Of these, ID1 and ID2 are associated with polymerase slippage during DNA replication and found in large numbers in cancers with mismatch repair deficiency." (PMID 35168570, 2022).
myeloid leukemia (1 paper, 2019). A clonal proliferation of myeloid cells and their precursors in the bone marrow, peripheral blood, and spleen. "Our ChIP data following co-expression of ASXL1 and RUNX1 mutations recognized the deregulation of ID1 in myeloid leukemia cells, suggesting the role of myeloid leukemia transformation by combined mutations were at least partly attributed to the upregulated ID1 expression." (PMID 31640815, 2019). "Notably, the leukemic cells from our patients harboring coexisted mutations of ASXL1 and RUNX1 correlated with the upregulation of ID1 gene expression, supporting the role of cooperative mutation of ASXL1 and RUNX1 on ID1 expression and myeloid leukemia transformation." (PMID 31640815, 2019).
myeloproliferative disease (1 paper, 2022). "Collectively, enforced expression of Id1 regulates HSPC fate by promoting myeloid and inhibiting lymphoid development in vitro and in vivo, and Id1 can promote HSPC proliferation and immortalize HSPCs in vitro, and promote a myeloproliferative disease in vivo." (PMID 35990659, 2022).
myocardial infarction (1 paper, 2017). Gross necrosis of the myocardium, as a result of interruption of the blood supply to the area, as in coronary thrombosis. "The transcriptional expression pattern of FoxM1, Id1, and Jnk3 was also determined in the whole heart following myocardial infarction (MI) injury." (PMID 28011860, 2017).
oesophageal cancer (1 paper, 2017). "Here we show that IGF2 secreted by inhibitor of differentiation (Id1)-overexpressing oesophageal cancer cells instigates VEGFR1-positive bone marrow cells in the tumour macroenvironment to form pre-metastatic niches at distant sites by increasing VEGF secretion from cancer-associated fibroblasts." (PMID 28186102, 2017).
orchitis (1 paper, 2021). Inflammation of one or both testes due to viral or bacterial infections. "On the other hand, Klf2, Klf4, Nfe2l2/Nrf2, Id1, Id2, Rad21, Xrcc1, and Cycs were found to be negatively correlated with androgen synthesis during orchitis." (PMID 35111154, 2021).
osteoarthritis (1 paper, 2014). A noninflammatory degenerative joint disease occurring chiefly in older persons, characterized by degeneration of the articular cartilage, hypertrophy of bone at the margins and changes in the synovial membrane. "ST samples immunostained for Id1 showed heightened expression in RA compared to osteoarthritis (OA) and normal (NL) ST." (PMID 24620998, 2014).
osteoporosis (1 paper, 2009). A condition of reduced bone mass, with decreased cortical thickness and a decrease in the number and size of the trabeculae of cancellous bone (but normal chemical composition), resulting in increased fracture incidence. "Yet, how Id1 deficiency contributes to aging-associated phenotypes, such as osteoporosis, has not been well characterized." (PMID 19956687, 2009). "This is a novel finding, as Id1 has not been previously linked to osteoporosis." (PMID 19956687, 2009). "Since proper bone remodeling is determined by a delicate balance between the bone-forming osteoblasts and the bone-resorbing osteoclasts, the observed osteoporosis in Id1−/− mice could be a consequence of decreased osteoblast activity, increased osteoclast activity, or both." (PMID 19956687, 2009).
otitis media (1 paper, 2021). Inflammation of the anatomical structures of the middle ear, which is most often caused by an infectious process. "More studies need to be done to clarify the underlying mechanism of otitis media in Id1/Id3 mutant mice." (PMID 34434211, 2021). "We speculate that Id1/Id3 mutations lead to an impaired immune system, which compromises the ability of the mutant mice to fight against middle ear inflammation, leading to continuous presence of effusion, epithelia hyperplasia and inflammatory cells." (PMID 34434211, 2021). "A total of 41 Id1−/−; Id3+/− mice, 14 Id1+/−; Id3−/− mice and 21 wild-type mice, aged 30 days, were randomly chosen to be screened for otitis media." (PMID 34434211, 2021). "Because of the upregulated expression of Id1 and Id3 in middle ears after the acute episode of pneumococcal otitis media has been resolved, the two genes are presumed to be involved in the development of otitis media." (PMID 34434211, 2021).
ovarian serous cystadenocarcinoma (1 paper, 2022). A malignant serous cystic epithelial neoplasm arising from the ovary. "We analyzed copy number alterations, mutations, methylations, and mRNA expressions of ID 1–4 and E2A using The Cancer Genome Atlas data of 570 ovarian serous cystadenocarcinoma patients." (PMID 35740568, 2022).
pancreatitis (1 paper, 2025). Inflammation of the pancreas. "BMP signalling induces the expression of Inhibitor of DNA binding 1 (ID1), which is known to be upregulated in pancreatitis and PDAC and is believed to have tumour-promoting effects by enabling bypassing of TGF-B signalling." (PMID 40826447, 2025).
periodontal diseases (1 paper, 2017). "The aging-related host responses that have been described so far for Id1 raise questions about its role in periodontal diseases, but currently very little is known." (PMID 29190775, 2017).
prostate adenocarcinoma (1 paper, 2012). "In contrast, high Id1 expression was observed in majority of prostate adenocarcinoma and was localized primarily to the glandular epithelial cells." (PMID 23342268, 2012). "Out of observed cases of 18 grade III prostatic adenocarcinoma, 17 specimens showed strong to moderate Id1 expression and one with no expression." (PMID 23342268, 2012).
pulmonary hypertension (1 paper, 2017). Increased pressure within the pulmonary circulation due to lung or heart disorder. "In addition, prostacyclin can inhibit the proliferation of smooth muscle cells, thereby preventing the progression of pulmonary hypertension and increase Smad1/5 phosphorylation and Id1 expression." (PMID 29348884, 2017).
sacral agenesis (1 paper, 2023). "The recent study reported a possible association between ID1 (inhibitor of DNA Binding 1) and non-syndromic sacral agenesis: the missense variants in ID1 were identified in two of three children (paternally inherited)." (PMID 36980147, 2023).
salivary gland cancer (1 paper, 2013). A primary or metastatic malignant neoplasm that affects the major or minor salivary glands. "Id1 suppression could represent a novel and effective approach for the treatment of salivary gland cancer." (PMID 23517130, 2013).
squamous cell carcinomas of the lung (1 paper, 2010). "In contrast, for the 9 matched squamous cell carcinomas of the lung, we observed overall greater average Id1 expression as compared to matched normal tissue, although these differences were not statistically significant (P = .65)." (PMID 20414347, 2010).
transient cerebral ischemia (1 paper, 2015). "This is the first study to show that ID1 is expressed in the GABAergic interneurons of the CA1 region following transient cerebral ischemia." (PMID 25503067, 2015). "In summary, immunoreactivity and the protein level of ID1 protein were apparently altered in the CA1 pyramidal neurons following transient cerebral ischemia, while ID4 immunoreactivity was detected in the microglia, but not the astrocytes, in the CA1 region following I-R." (PMID 25503067, 2015).
tubular adenoma (1 paper, 2023). A usually polypoid neoplasm arising from the glandular epithelium. "GREMLIN1 expression was significantly upregulated, while the inhibitor of DNA binding (ID) proteins ID1, ID2, ID3 and ID4, all major downstream transcription targets of BMP signaling, were found to be significantly downregulated in serrated adenomas compared to tubular adenomas." (PMID 36326956, 2023).
Ureteral obstruction (1 paper, 2016). Obstruction of the flow of urine through the ureter. "It has been reported that ID1 expression is induced exclusively in the degenerated, dilated renal tubular epithelium after unilateral ureteral obstruction." (PMID 27127787, 2016).
Uterine leiomyoma (1 paper, 2016). The presence of a leiomyoma of the uterus. "Our study is the first study to reveal ID1 expression in human uterine leiomyoma cells downstream of histone H3 phosphorylation induced by genistein." (PMID 27582276, 2016). "Therefore, ID1 might work in uterine leiomyoma tumorigenesis through histone H3 activity." (PMID 27582276, 2016).
tumor (300 papers, 2004 to 2026). "A comparative analysis of ID1, ID2 and ID3 expression further implicated ID1 as the dominant family member during disease progression with a 10‐fold higher expression in the primary tumour that increased further during metastasis." (PMID 40116596, 2025). "A key downstream effector is ID1, a transcriptional regulator associated with tumor cell invasion and stem‐like behavior." (PMID 40781861, 2025). "This anti-tumor activity depended on trametinib-mediated Id1 reduction and was associated with a less immunosuppressive tumor microenvironment and increased PD-L1 expression on tumor cells." (PMID 38643157, 2024). "Patient-derived tumor spheroids exhibited a functional association between autophagy, ID1, SLC31A1, and platinum sensitivity." (PMID 39123206, 2024). "In tumor cells, increased levels of ID1 are associated with a poorly differentiated and aggressive phenotype, and ID1 affects cell survival and metastasis by regulating multiple pathways." (PMID 39052126, 2024). "Increased expression of ID1 has been associated with both primary tumor formation and lung colonization presumably via mesenchymal–epithelial transition essential for the latter process." (PMID 37518985, 2023). "In NSCLC patients, Id1 has been associated with poor response and prognosis, as it plays a central role in tumorigenesis, tumor angiogenesis, metastasis, and tumor progression, suppressing the antitumor immune response." (PMID 37841258, 2023). "Id1 absence in the tumor microenvironment in Id1-deficient mice significantly increased the tumor infiltration of CD3+ T cells, and more importantly, effector CD8+ T cells, as compared to Id1-expressing mice (CD3+ T cells p > 0.0001; CD8+ T cells p > 0.0001)." (PMID 37841258, 2023). "Id1 gene silencing can ablate bone marrow-derived EPCs and cause obvious defects in angiogenesis-mediated tumor growth." (PMID 35049366, 2022). "Accumulating evidences indicated that ID1 was associated with tumor progression through an aberrant change of cell behaviors." (PMID 35635748, 2022). "According to our in silico analyses, BMP‐9‐mediated induction of ID1 should have tumour‐suppressive effects, while noggin should cause tumour‐promoting changes." (PMID 34841646, 2022). "Tumor overexpression of ID1, which encodes a DNA-binding protein inhibitor (effectively eliminating its DNA-binding ability) is also known to predict node metastasis." (PMID 33650835, 2021). "Initial data associating ID1 and ID3 with cancer emerged from studies of xenografts and spontaneous tumors in genetically engineered mouse models, which typically showed decreased tumor growth and impaired angiogenesis in Id1- and/or Id3-deficient backgrounds." (PMID 34031428, 2021). "ID1 is one of the most investigated members of the ID family, and recent researches have shown that ID1 is associated with invasion, tumor malignancy, undifferentiation, and poor prognosis in several cancers." (PMID 33178820, 2020). "It is reported that ID1 is associated with tumorigenesis and tumor metastasis, but how ID1 affects ccRCC still remains unexplained." (PMID 33178820, 2020). "Our previous work has revealed that the expression of the dominant negative transcriptional regulator Id1 is a biomarker of poorer prognosis as it is associated with tumor progression, metastasis formation, and tumor-immunosuppression in KRAS-driven NSCLC." (PMID 33126649, 2020). "To determine the mechanisms involved in the antitumor activity observed in response to the Id1-loss in combination with the blockade of PD-1/PD-L1 axis, we evaluated the changes induced in the tumor microenvironment by the combined blockade." (PMID 33126649, 2020). "ID1 overexpression is associated with tumor angiogenesis and poor clinical outcome in oral squamous cell carcinoma." (PMID 32246075, 2020).
tumor (continued). "ID1 is associated with regulation of endothelial cell differentiation and angiogenesis, as well as mobilization of endothelial cells, which can aid in tumor survival and metastasis." (PMID 31953577, 2020). "It was identified that CRTC2 is upregulated in LKB1-deficient NSCLC, promoting tumor growth via the induction of ID1." (PMID 32516941, 2020). "In breast cancer cell lines, vitamin D signaling inhibits expression of a tumor progression gene (Id1), and ablation of VDR expression causes increased tumor growth and development of metastases." (PMID 31252594, 2019). "A univariate analysis revealed that tumor size, tumor number, vascular invasion, Id-1 and CCN2 expression were significantly associated with the post-operative OS and CCR of HCC patients." (PMID 31250351, 2019). "Src activation is associated with tumor progression, invasion, metastasis as well as therapy resistance in PDACs and it is known to induce Id1 expression." (PMID 31100813, 2019). "Resistance to tumor angiogenesis was reported in mice deficient in 1–3 alleles of ID1/ID3 gene knockout combination." (PMID 28785583, 2017). "Numerous studies have shown that Id-1 (Inhibitor of differentiation 1) is upregulated in several cancers and associated with tumor malignant characters." (PMID 29233161, 2017). "The results showed that the upregulation of Id-1 were significantly associated with larger tumor size (p = 0.028), lymph node metastasis (p = 0.018) and advanced TNM stage (p = 0.005)." (PMID 29233161, 2017). "This would support a role of Id1 and its isoform in tumor initiation by promoting self-renewal properties by the spliced Id1 variant and, subsequently, proliferation by canonical Id1." (PMID 28122577, 2017). "Restrained tumor growth was associated with a prominent decrease in tumor vascularity (blood and lymph vessels), likely due to reduced Id1 expression, a transcription factor highly implicated in VEGF-A and VEGF-C gene regulation." (PMID 27732945, 2016). "Inhibition of Id1 in the bone marrow (BM) results in significant decreases in endothelial progenitor cell (EPC)-linked tumor-associated vasculogenesis." (PMID 27071670, 2016). "Because the loss of Id2 specifically suppresses ileal tumor initiation in ApcΔ716 mice, we confirmed the expression patterns of Id2 and other Id-family members (Id1 and Id3) along the proximal-distal axis of the small intestine." (PMID 26163528, 2015). "Inhibitor of DNA binding (ID) proteins are transcriptional targets of TGF-β1 and ID1 has been implicated in VEGF-A regulation during tumor angiogenesis." (PMID 26577912, 2015). "Id proteins, especially Id1, are associated with a more aggressive and invasive behavior, as well as with a less differentiated tumor phenotype, and in some kinds of tumors, as markers of cancer diagnosis and progression." (PMID 23517130, 2013). "By staining each of the PDICs that had been previously identified by their loss of insulin, we determined that tumor cells in all PDICs were positive for Id1." (PMID 23691228, 2013). "Sequence analyses of the HD and PEST regions in Notch1 transcripts expressed in Id1 tumor samples revealed such mutations at frequencies of 17% and 60% respectively." (PMID 22393458, 2012). "Loss of Id1 in the BM leads to a complete loss of EPCs in peripheral blood, which has been correlated with a block in tumor neovascularization and delayed tumor growth." (PMID 20796276, 2010). "Since Id1 has been implicated in promoting tumor cell migration and invasion, cellular migration was evaluated in H23 cells expressing Id1 in both a scratch assay and a transwell migration assay." (PMID 20414347, 2010). "Depending on the tumour art and stage, partial loss of Id functions is sufficient to have a therapeutic effect, as shown in Id1+/−Id3−/− knockout mice." (PMID 20842131, 2010).